SLIT2 (slit guidance ligand 2)
Description:
Thought to act as molecular guidance cue in cellular migration, and function appears to be mediated by interaction with roundabout homolog receptors. During neural development involved in axonal navigation at the ventral midline of the neural tube and projection of axons to different regions. SLIT1 and SLIT2 seem to be essential for midline guidance in the forebrain by acting as repulsive signal preventing inappropriate midline crossing by axons projecting from the olfactory bulb. In spinal cord development may play a role in guiding commissural axons once they reached the floor plate by modulating the response to netrin. May be implicated in spinal cord midline post-crossing axon repulsion. In vitro, only commissural axons that crossed the midline responded to SLIT2. In the developing visual system appears to function as repellent for retinal ganglion axons by providing a repulsion that directs these axons along their appropriate paths prior to, and after passage through, the optic chiasm. In vitro, collapses and repels retinal ganglion cell growth cones. Seems to play a role in branching and arborization of CNS sensory axons, and in neuronal cell migration. In vitro, Slit homolog 2 protein N-product, but not Slit homolog 2 protein C-product, repels olfactory bulb (OB) but not dorsal root ganglia (DRG) axons, induces OB growth cones collapse and induces branching of DRG axons. Seems to be involved in regulating leukocyte migration.
Synonyms: Slit-2; SLIL3
Tractability: Small molecule: it has a binding pocket of medium quality. Antibody: UniProt places it where antibodies can reach, with high confidence; its Gene Ontology location is reachable by antibodies, with high confidence; UniProt predicts a signal peptide or a membrane-spanning region. PROTAC: its protein half-life has been measured.
Gene: Protein-coding gene on chromosome 4 (20,251,903 to 20,620,561, forward strand). Ensembl gene ENSG00000145147.
Subcellular location: Secreted
Pathways (Reactome):
Developmental Biology: Activation of RAC1; Formation of the ureteric bud; Inactivation of CDC42 and RAC1; Netrin-1 signaling; Regulation of commissural axon pathfinding by SLIT and ROBO; Regulation of expression of SLITs and ROBOs; Role of ABL in ROBO-SLIT signaling; SLIT2:ROBO1 increases RHOA activity; Signaling by ROBO receptors
Gene Ontology:
Molecular function: GTPase inhibitor activity; heparin binding; identical protein binding; laminin-1 binding; protein binding; protein homodimerization activity; proteoglycan binding; Roundabout binding; calcium ion binding; chemorepellent activity
Biological process: apoptotic process involved in luteolysis; axon extension involved in axon guidance; axon guidance; branching morphogenesis of an epithelial tube; cell migration involved in sprouting angiogenesis; cellular response to heparin; cellular response to hormone stimulus; chemorepulsion involved in embryonic olfactory bulb interneuron precursor migration; chemorepulsion involved in postnatal olfactory bulb interneuron migration; corticospinal neuron axon guidance through spinal cord; induction of negative chemotaxis; motor neuron axon guidance; negative chemotaxis; negative regulation of actin filament polymerization; negative regulation of cell growth; negative regulation of cell migration; negative regulation of cellular response to growth factor stimulus; negative regulation of chemokine-mediated signaling pathway; negative regulation of endothelial cell migration; negative regulation of lamellipodium assembly; negative regulation of leukocyte chemotaxis; negative regulation of mononuclear cell migration; negative regulation of neutrophil chemotaxis; negative regulation of protein phosphorylation; negative regulation of retinal ganglion cell axon guidance; and 23 more
Cellular component: cytoplasm; extracellular exosome; extracellular region; membrane; non-collagenous component of interstitial matrix
Genetic constraint (gnomAD): Loss-of-function variants: 19 observed, 123.21 expected, observed/expected ratio (o/e) 0.15, 90% interval 0.11 to 0.23. The upper end of that interval is the gene's LOEUF score, 0.23, which puts it in group 1 of 6, group 1 being the genes least tolerant of losing a copy. Missense variants: 1,151 observed, 1,480.1 expected, observed/expected ratio (o/e) 0.78, 90% interval 0.74 to 0.82. Synonymous variants: 541 observed, 537.48 expected, observed/expected ratio (o/e) 1.01, 90% interval 0.94 to 1.08.
Homologues: Orthologues: chimpanzee SLIT2 (99% identical), macaque SLIT2 (99% identical), pig SLIT2 (98% identical), rabbit SLIT2 (98% identical), rat Slit2 (97% identical), mouse Slit2 (97% identical), dog SLIT2 (96% identical), tropical clawed frog slit2 (88% identical), guinea pig SLIT2 (85% identical), zebrafish slit2 (79% identical). Paralogues in human: SLIT3 (66% identical), SLIT1 (66% identical), TLR9 (11% identical), LRFN5 (10% identical), SLITRK5 (10% identical), LRRN3 (10% identical), LRRN1 (10% identical), SLITRK2 (10% identical), LRFN1 (10% identical), SLITRK3 (10% identical), LRFN3 (10% identical), LRRN2 (10% identical), and 13 more.
Diseases named in the same sentence as SLIT2 in open-access papers:
SLIT2 is named in the same sentence as 174 diseases in open-access papers, as found by Europe PMC text mining. Sharing a sentence is not in itself a finding about the gene and the disease. The quoted sentences say what the papers report.
breast carcinoma (60 papers, 2004 to 2025). "More recently, SLIT2 has been shown to inhibit metastasis in breast cancer by activating M1-Like phagocytic tumor-associated macrophages (M1-TAMs), and high SLIT2 expression correlates with better patient survival." (PMID 40508075, 2025). "Another study demonstrated that decreased expression of SLIT2 is associated with a poor prognosis and brain-specific metastasis in breast cancer patients." (PMID 32795291, 2020). "The methylation of SLIT2 was associated with the development and progression of hepatocellular carcinoma, dysplasia of pancreatic cystic neoplasms, breast cancer, and nasopharyngeal carcinoma." (PMID 31956659, 2019). "Slit2 overexpressing breast cancer cells displayed the reduced tumor growth and Slit2 or Robo1-deficient mammary epithelium led to hyperplasia after xenografts transplantation." (PMID 26400100, 2015). "SLIT2 was usually regarded as a tumor suppressor gene and silenced both in colorectal cancer and breast cancer, whose silence was caused by the hypermethylation of its promoter regions and allelic loss." (PMID 25774687, 2015). "In terms of oncogenes, ROBO2 (roundabout, axon guidance receptor, 2), a receptor of the SLIT2 axon guidance and cell migration growth factor, is associated with poor prognosis of breast cancer." (PMID 20015385, 2009). "Cluster 110 contains genes that have previously been associated with chemotaxis and invasion of breast cancer cell lines (SLIT2, RECK), as well as genes related to the extracellular matrix (ECM2, COL4A1)." (PMID 18498629, 2008). "On the contrary, the loss of SLIT2 functions through gene deletion, epigenetic inactivation, and mutations could increase the risk of various cancers, including breast cancer." (PMID 39596804, 2024). "Although Slit2/Robo1 is linked to aberrant growth and migration of tumor epithelial cells, which consequently resulted in metastatic spread of cancer cells, the clinical significance of this axis in brain metastasis of breast cancer is unknown." (PMID 26400100, 2015). "SLIT2 is aberrantly expressed in human pancreatic cancer and highly metastatic breast cancer, and it has been demonstrated to inhibit neural invasion." (PMID 40092993, 2025). "In breast cancer models, SLIT2 expression is substantially elevated in the endothelial cells of highly metastatic breast cancer, and its elimination dramatically diminishes tumor innervation." (PMID 40092993, 2025). "Together with other reports that GREM1 can activate epidermal growth factor (EGF) receptor in breast cancer cells and bind to slit guidance ligand-2 (SLIT2) in neurons, a somewhat muddied picture exists of GREM1 biology and signaling in health and disease." (PMID 41033552, 2025). "In contrast, the interaction of SLIT2-ROBO inhibits breast cancer cell chemotaxis, chemo invasion, and adhesion." (PMID 37238655, 2023). "Overexpression of ROBO1 has been shown in breast carcinoma tissue samples, and SLIT2 stimulates migration in breast cancer cell lines." (PMID 37238655, 2023). "In the breast cancer mouse model, Slit2 was observed to reduce fibrosis by upregulating the expression of matrix metalloproteinase 13 in M1-type tumor associated macrophages (TAMs)." (PMID 37950728, 2023). "The SLIT2/ROBO1 pathway inhibits cell invasion by interacting with E-cadherin and β-catenin in breast cancer and colorectal cancer, whereas in liver cancer, SLIT2/ROBO1 specifically inhibits hepatocyte growth factor (HGF)–mediated cell migration." (PMID 36498797, 2022). "A growing body of literature has shown that the activation of the Slit2/Robo1 axis can suppress the proliferation and invasion of multiple cancers, including cervical, colorectal and breast cancers." (PMID 33621954, 2021). "Enhancer RNA SLIT2 was shown to be lowly expressed in breast cancer, and its knockdown suppressed the proliferative and metastatic abilities of breast oncocytes via modulating P38 MAPK/c-Fos signal path." (PMID 35003394, 2021).
breast carcinoma (continued). "Using a spontaneous mammary tumor virus promoter-polyoma middle T antigen (PyMT) breast cancer mouse model, we observed that Slit2 increased the abundance of antitumor M1 macrophage in the bone marrow upon differentiation in vitro." (PMID 34777365, 2021). "Slit2 treatment also altered mitochondrial respiration metabolites in macrophages isolated from healthy human blood that were treated with plasma from breast cancer patients." (PMID 34777365, 2021). "Other studies on gastric and breast cancer suggest that SLIT2 executes its tumor suppressive function via the regulation of the AKT/β-catenin signaling pathway." (PMID 33120864, 2020). "A tumor-repressive activity has been attributed to Slit2, and the Slit2 promoter region is hypermethylated in primary lung cancer, breast cancer, and colorectal carcinomas." (PMID 29864155, 2018). "Full-length Slit2 was undetectable in lungs homogenates of both control and 4T1 breast cancer-bearing mice, while its N-terminal fragment was found both in healthy control and breast-cancer bearing mice." (PMID 30075800, 2018). "CAF‐derived SLIT2 suppresses invasion of breast cancer cells expressing its receptor roundabout homolog 1 (ROBO1), through inhibition of PI3K and β‐catenin signaling." (PMID 29280568, 2018). "The loss of SLIT2, SLIT3, or ROBO1 protein in mouse breast cancer models results in an increase in repair processes in tissues, promoting cell proliferation." (PMID 29743814, 2018). "In many different carcinomas, such as colorectal, lung, kidney, and mammary carcinoma, the promoter for Slit2 is mostly hypermethylated." (PMID 29864155, 2018). "SLIT2 also has tumor suppressive activity and is frequently inactivated in multiple carcinomas, including breast cancer." (PMID 29757932, 2018). "The Slit2/Robo1 (or Robo2) system is involved in the guided migration of breast cancer cells and is suspected to mediate their metastasis into the brain." (PMID 29864155, 2018). "Slit2 also acts as a tumor suppressor by maintaining E-Cadherin/β-Catenin functions in breast cancer." (PMID 26572553, 2015). "Recently, Slit2/Robo1 pathway has been demonstrated to be involved in the progression of breast carcinoma." (PMID 26400100, 2015). "Overall, our findings indicated that Slit2/Robo1 axis possibly be regarded as a significant clinical parameter for predicting brain metastasis in breast cancer patients." (PMID 26400100, 2015). "In this present study, we provided new evidence that Slit2/Robo1 axis is a suppressor of breast cancer progression." (PMID 26400100, 2015). "In breast cancer, SLIT2 blocks a whole host of SDF1-induced signaling involved in motility such as the activation MAP kinase or focal adhesion components." (PMID 26674478, 2015). "The median interval from diagnosis of breast cancer to brain metastasis in patients with low expression of Slit2 (14 months) was much shorter than the high Slit2-expression group (31 months, Z = −3.146, P = 0.002)." (PMID 26400100, 2015). "The validation data confirmed that mRNA expression levels of Slit2 and Robo1 were down-regulated in breast cancer tissues compared with their corresponding normal tissues (P < 0.01)." (PMID 26400100, 2015). "Slit2 promoter hypermethylation in tissue and serum samples from breast cancer patients was a possible marker for early detection." (PMID 26400100, 2015). "In this study, we investigated the correlation between Slit2/Robo1 signaling and breast cancer brain metastasis for the first time." (PMID 26400100, 2015). "In order to confirm the role of Slit2/Robo1 in breast cancer, we performed the migration assays in vitro." (PMID 26400100, 2015). "Taken together, our studies demonstrate a novel role for Slit2/Robo1 axis in brain metastasis of breast cancer and probably provide a new therapeutic option in patients with brain metastasis." (PMID 26400100, 2015).
breast carcinoma (continued). "To explore the prognostic significance of Slit2/Robo1 axis in breast cancer patients, we analyzed 118 IDC patients with complete clinical follow-up." (PMID 26400100, 2015). "Ectopic SLIT2 expression in breast cancer cells inhibits tumor cell migration and tumor growth in engrafted mice models through a mechanism implicating β-catenin modulation." (PMID 26674478, 2015). "The relationship between Slit2 or Robo1 expression and breast cancer brain metastasis was further investigated in an enlarged cohort of 33 IDC patients with brain metastasis and 110 IDC patients without brain metastasis." (PMID 26400100, 2015). "Next, we analyzed mRNA expression levels of Slit2 and Robo1 in gene expression profiling data sets from breast cancer and normal tissues." (PMID 26400100, 2015). "Both, NFs and CAFs expressing the ligand Slit2 inhibited the tumorigenicity of breast cancer cells expressing the corresponding Robo1-receptor on their surface." (PMID 24734219, 2014). "Slit2/Robo1 signaling can promote glioma cell migration and metastasis of breast cancer cells to the brain." (PMID 21301049, 2010). "In breast carcinoma tissue samples ROBO1 was shown to be overexpressed while SLIT2 induced migration of breast cancer cell lines." (PMID 19114000, 2008). "Recently, we identified frequent promoter region hypermethylation of SLIT2 in lung and breast cancers." (PMID 14735202, 2004). "Slit2 also increases the expression of matrix metalloproteinases in M1-TAMs, which attenuates fibrosis in a mouse model of breast cancer.High expression of Slit2 correlates with improved survival and is negatively correlated with the density of CD163 + TAMs in patient samples." (PMID 39068459, 2024). "In this study, we used a breast cancer model to examine the effects of radiation alone or in combination with estrogens on the expression of genes linked to cell motility, such as ADAM12, CYR61, FLRT2, SLIT2, VNN1, MYLK, MAP1B, and TUBA1A." (PMID 39596804, 2024). "Slit2, a secretory glycoprotein, has been found to inhibit breast cancer progression; however, the specific mechanism remains unknown." (PMID 37491279, 2023). "However, the inhibitory effects of SLIT2 on cancer progression and metastasis have also been reported in pancreatic cancer, lung cancer, breast cancer and thyroid cancer." (PMID 37443302, 2023). "Furthermore, the possible regulatory signaling pathway of SLIT2 in breast cancer bone metastasis was identified providing a favorable therapeutic strategy for metastasis of breast cancer." (PMID 36287118, 2022). "Expressions of SLIT2 and ROBO1 are downregulated in ductal carcinoma in situ and invasive breast cancer tissues, and such downregulation is associated with poor prognosis and brain metastasis of breast cancer." (PMID 35053460, 2022). "In breast cancer, SLIT2 has a tumor-suppressing effect by enhancing cell adhesion." (PMID 35996510, 2022). "Slit2 has also been shown to inhibit breast cancer by enhancing phagocytosis and reducing fibrosis." (PMID 34777365, 2021). "In mouse models of breast cancer and lung cancer, the deletion of SLIT2 inhibited metastasis." (PMID 34007851, 2021). "MiR-218 represses invasion and migration of breast cancer cells by Slit2/Robo1 signaling." (PMID 33686957, 2021). "The human breast cancer PCR array detected significantly increased expression of SLIT2 (slit guidance ligand 2) and decreased expression of IGF1 (insulin-like growth factor 1) and TWIST1 (twist family BHLH transcription factor 1) with 3-fold changes in the expression levels." (PMID 32565805, 2020). "While Slit2 is expressed in metastatic breast cancer cells, it is associated with metastasis to brain but not to bone whereas both estrogen and Wnt signaling are linked to bone metastasis." (PMID 27738322, 2016). "Furthermore, in breast cancer cells, SLIT2 also inhibits tumor cell migration by affecting the direction of migration through the deubiquitylating enzyme USP33." (PMID 26674478, 2015).